CDH16 (cadherin 16)
Description:
Cadherins are calcium-dependent cell adhesion proteins. They preferentially interact with themselves in a homophilic manner in connecting cells; cadherins may thus contribute to the sorting of heterogeneous cell types.
Tractability: Antibody: UniProt places it where antibodies can reach, with high confidence; UniProt predicts a signal peptide or a membrane-spanning region; its Gene Ontology location is reachable by antibodies, with medium confidence.
Gene: Protein-coding gene on chromosome 16 (66,908,122 to 66,919,187, reverse strand). Ensembl gene ENSG00000166589.
Subcellular location: Cell membrane
Gene Ontology:
Molecular function: protein binding; cell adhesion molecule binding; calcium ion binding
Biological process: cell adhesion; cell-cell adhesion; homophilic cell-cell adhesion
Cellular component: extracellular exosome; plasma membrane; synapse; basolateral plasma membrane; membrane
Genetic constraint (gnomAD): Loss-of-function variants: 78 observed, 87.26 expected, observed/expected ratio (o/e) 0.89, 90% interval 0.74 to 1.08. The upper end of that interval is the gene's LOEUF score, 1.08, which puts it in group 4 of 6, group 1 being the genes least tolerant of losing a copy. Missense variants: 1,124 observed, 1,104 expected, observed/expected ratio (o/e) 1.02, 90% interval 0.97 to 1.07. Synonymous variants: 457 observed, 456.55 expected, observed/expected ratio (o/e) 1, 90% interval 0.93 to 1.08.
Homologues: Orthologues: chimpanzee CDH16 (98% identical), macaque CDH16 (92% identical), pig CDH16 (80% identical), dog CDH16 (80% identical), mouse Cdh16 (78% identical), rat Cdh16 (77% identical), guinea pig CDH16 (73% identical). Paralogues in human: PCDHGA7 (25% identical), PCDHB11 (25% identical), PCDHGA11 (25% identical), PCDHB12 (25% identical), PCDHGA3 (25% identical), PCDHB7 (24% identical), PCDHGA2 (24% identical), PCDHGA4 (24% identical), PCDHGA6 (24% identical), PCDHB14 (24% identical), PCDHB2 (24% identical), PCDHB3 (24% identical), and 49 more.
Diseases named in the same sentence as CDH16 in open-access papers:
CDH16 is named in the same sentence as 51 diseases in open-access papers, as found by Europe PMC text mining. Sharing a sentence is not in itself a finding about the gene and the disease. The quoted sentences say what the papers report.
renal cell carcinoma (5 papers, 2005 to 2024). "In an earlier comparative study, our group had identified CDH16 as a suitable marker for the distinction of renal cell carcinomas from other tumor entities." (PMID 39105782, 2024). "A recent study has shed light on the prognostic significance of CDH16 in renal cell carcinoma, where a reduction in CDH16 expression was identified as a potent predictor of poor prognosis." (PMID 37899424, 2023). "The most commonly CDH16 positive cancers included renal cell carcinomas, nephrogenic adenomas, and follicular neoplasms of the thyroid, followed by tumors of the female genital tract and various categories of neuroendocrine tumors." (PMID 37558687, 2023). "Only a small number of studies have used immunohistochemistry to analyze CDH16 expression in cancer and these were limited to renal cell carcinomas (RCC)." (PMID 37558687, 2023). "The combination of PAX8 and CDH16 positivity has high specificity for renal cell carcinoma." (PMID 39105782, 2024). "Our data suggest that CDH16 immunohistochemistry may be useful for the distinction of renal cell carcinomas from other neoplasms." (PMID 37558687, 2023). "For the distinction between renal cell carcinomas and urothelial carcinomas, sensitivity was 86.7% and specificity 91.3% for PAX8, while sensitivity was 82.7% and specificity 99.8% for CDH16." (PMID 39105782, 2024). "Although CDH16 is not specific for renal cell carcinomas and can also be seen in gynecological, neuroendocrine and several other tumors, it is noteworthy that CDH16 expression is mostly weak and not involving all cells in these extrarenal neoplasms." (PMID 37558687, 2023).
renal fibrosis (5 papers, 2017 to 2025). A final common manifestation of a wide variety of chronic kidney diseases characterized by glomerulosclerosis and tubulointerstitial fibrosis. "We further evaluated renal fibrosis by IHC staining of αSMA, and results indicated that kidneys from Cdh16-ARKO mice exhibited a decreased number of myofibroblasts, compared with kidneys from WT mice." (PMID 30894518, 2019). "To further explore the relevance and mechanism of PC in renal fibrosis, we used CRISPR‐Cas9 technology to create a model of conditionally knocked‐out PC in tubular epithelial cells of mice (Pcxflox/flox;Cdh16‐Cre, PcxcKO)." (PMID 39836535, 2025). "To determine whether S4KO alleviates renal fibrosis by upregulating the acetylation of U2AF2 in mouse kidney, we crossed Cdh16-cre/ERT2×U2af2flox/flox (U2af2-/-) with Sirt4-/- mice to generate DKO mice and then performed UUO surgery." (PMID 39495216, 2024).
cyst (4 papers, 2017 to 2023). A sac-like closed membranous structure that may be empty or contain fluid or amorphous material. "Further, increased cell proliferation and myofibroblast activation occurred early during disease progression and preceded detectable cyst formation in the Invsflox/flox;Cdh16-Cre kidney." (PMID 36920028, 2023). "We therefore performed a detailed time course analysis of cyst formation and the fibrotic response in the Invsflox/flox;Cdh16-Cre kidney." (PMID 36920028, 2023). "At P21, cilia were present in cyst-lining DBA positive cells as indicated by immunostaining with the cilia marker anti-acetylated tubulin in the Invsflox/flox;Cdh16-Cre kidney." (PMID 36920028, 2023). "However, since the onset of fibrosis and cyst formation overlap in the Arl13bflox/flox;Cdh16-Cre model, it is difficult to address whether interstitial fibrosis is solely secondary to epithelial cyst formation through, for example, mechano-stress exerted by expanding cysts." (PMID 36920028, 2023). "We validated the clustering outcomes by using specific antibodies for different nephron segments, including LRP2, SLC12A1, CDH16, KRT17 and two classical markers CD10 and AQP2(the marker of PT and CD, respectively) for IHC staining of cyst epithelial cells." (PMID 34815804, 2021). "We studied the cell origin of cyst epithelial cells by conducting differential gene expression analysis and established genetic markers (LRP2, SLC12A1, CDH16, and KRT17) 21, 22 of renal tubules and CD in the epithelial cell populations, respectively." (PMID 34815804, 2021).
thyroid cancer (4 papers, 2016 to 2025). "These questions are relevant to our understanding of sensory gating and the development of the CS, but also for cancer biology, as cdh16 is downregulated in thyroid carcinomas and limits thyroid carcinoma cell proliferation." (PMID 40315416, 2025). "Some the poor prognosis genes identified, such as TFF3 and CDH16, represent well-established thyroid cancer markers." (PMID 27633254, 2016). "Several hypermethylated genes (GALNTL6, HTR7, SPOCD1, CDH16 and GRM5) related to thyroid cancer have been discovered to be up-regulated in our study, as were investigated in other reports to mentioned in the following text." (PMID 35267472, 2022).
follicular adenomas (3 papers, 2009 to 2023). "In the thyroid, CDH16 staining was seen in 100% of normal samples, 86% of follicular adenomas, 60% of follicular carcinomas, but only 7% of papillary carcinomas (p < 0.0001)." (PMID 37558687, 2023). "In thyroid tissues, there was a significant decrease of CDH16 positivity from normal thyroid (8 of 8 positive, 100%) to follicular adenomas (81 of 94, 86.2%), follicular carcinomas (40 of 67, 59.7%) and papillary carcinomas (14 of 212, 6.6%; (p < 0.0001)." (PMID 37558687, 2023). "In all cases except one (CASP10, F-test, p<0.05), the gene expression level differentiated not only between macro- and micro-follicular adenomas but also between follicular adenomas and oncocytic adenomas, as in the case of CDH16 and CRABP1 genes." (PMID 19893615, 2009).
Oncocytoma (3 papers, 2009 to 2023). "In renal cell tumors, CDH16 positivity was significantly more frequent in oncocytoma (104 of 106 positive, 98%) and chromophobe cancers (64 of 66, 97%) than in clear cell (384 of 452, 85%) and papillary renal cell carcinomas (105 of 138, 76%; p < 0.0001)." (PMID 37558687, 2023). "They described CDH16 positivity in 0% to 95% of 6–41 analyzed oncocytomas 10–14,17, 5.6% to 100% of 7–36 chromophobe RCCs10–15,17, 0% to 29% of 14–46 papillary RCCs10–13,16, and 0% to 30% of 15–102 clear cell RCCs10–15." (PMID 37558687, 2023). "In analogy to the higher staining intensity in distal than in proximal tubuli of the normal kidney, the CDH16 staining was generally more intense in oncocytomas and chromophobe carcinomas—both derived from distal tubuli—than in papillary and clear cell carcinomas arising from proximal tubuli." (PMID 37558687, 2023).
renal carcinoma (3 papers, 2013 to 2023). A carcinoma arising from the epithelium of the renal parenchyma or the renal pelvis. "The parallel observed between thyroid tumors and renal carcinomas in terms of CDH6 and CDH16 expression would suggest that these tumor types share at least a part of the mechanisms governing tumor progression." (PMID 24069422, 2013). "Although CDH16 expression differences between renal cancer subtypes are statistically significant, our data do not suggest a relevant practical utility of CDH16 immunohistochemistry for subtype distinction at the selected experimental conditions." (PMID 37558687, 2023).
cystic kidney (2 papers, 2023 to 2024). "By contrast, stage-matched Invsflox/flox;Cdh16-Cre single mutants had enlarged and severely cystic kidneys, with significantly increased KBW ratios and cystic index." (PMID 36920028, 2023).
follicular carcinomas (2 papers, 2023). "A possible role of reduced CDH16 expression for a subset of follicular thyroidal neoplasms is consistent with the 13.8% adenomas and the 40.3% follicular carcinomas with CDH16 negativity in this study." (PMID 37558687, 2023).
papillary carcinomas of the thyroid (2 papers, 2023). "Considering the unequivocal and strong CDH16 staining in all normal thyroid samples, as well as the CDH16 expression loss in more than 90% of our papillary carcinomas, CDH16 loss appears to constitute a strong argument in favor of a papillary carcinoma." (PMID 37558687, 2023). "Our data suggest CDH16 as a potential diagnostic marker—as a part of a panel—for the identification of papillary carcinomas of the thyroid, nephrogenic adenomas, and the distinction of renal cell tumors from other neoplasms." (PMID 37558687, 2023). "Downregulation of CDH16 RNA was found in papillary carcinomas of the thyroid." (PMID 37558687, 2023).
renal cyst (2 papers, 2023 to 2024). A fluid filled sac in the kidney. "Consistent with previous reports, Ift88flox/flox;Cdh16-Cre single knockout mice showed a slower progression of renal cystic disease in comparison to Invsflox/flox;Cdh16-Cre mutants." (PMID 36920028, 2023). "Together, these results reveal a progressive renal cystic disease in Invsflox/flox;Cdh16-Cre mice." (PMID 36920028, 2023).
renal failure (2 papers, 2019 to 2025). "In addition, variant alleles of CDH16 and COL8A1 genes in Schnauzers might be an important link in understanding the high incidence of renal failure in Miniature Schnauzers, which are considered to have a breed predisposition to renal diseases." (PMID 31842489, 2019).
thyroid tumor (2 papers, 2013 to 2023). A benign or malignant neoplasm affecting the thyroid gland. "The functional role of CDH16 expression loss in thyroid neoplasms is unclear." (PMID 37558687, 2023). "Given the predilection of CDH16 RNA expression to the kidney and the thyroid, CDH16 antibodies may be useful for the distinction of renal or thyroidal neoplasms from other cancers." (PMID 37558687, 2023).
cervical adenocarcinoma (1 paper, 2023). An adenocarcinoma arising from the cervical epithelium. "Given the conspicuously high rate of CDH16 positive cervical adenocarcinomas as compared to the paucity of CDH16 positive cells in normal endocervical epithelium, significant CDH16 positivity may argue for malignancy at this location." (PMID 37558687, 2023).
cholangiocarcinoma (1 paper, 2016). A carcinoma that arises from the intrahepatic biliary tree (intrahepatic cholangiocarcinoma) or from the junction, or adjacent to the junction, of the right and left hepatic ducts (hilar cholangiocarcinoma). "These metastases were positive for PAX8, that is a well-established marker for primary and metastatic RCC and CDH16, which is a specific renal protein, while they were negative for the bile ducts and cholangiocarcinoma marker CK7 (Cytokeratin 7), consistent with their renal origin." (PMID 27668431, 2016).
endocervical adenocarcinoma (1 paper, 2023). An adenocarcinoma that arises from the endocervix. "The same applies for a potential diagnostic utility of CDH16 IHC in endocervical adenocarcinomas." (PMID 37558687, 2023).
Hypocalcemia (1 paper, 2025). An abnormally decreased calcium concentration in the blood. "In cdh16 mutants, overexpressed Stc1l functions to suppress Papp-aa and ionocyte proliferation, and ultimately promotes hypocalcemia and hyper-responsiveness to acoustic stimuli." (PMID 40315416, 2025).
Infertility (1 paper, 2026). "A total of 56.7% Cdh16-Cre+; Frmd5flox/flox mice failed to form vaginal lumen and developed longitudinal vaginal septum coupled with infertility in these mice." (PMID 42003911, 2026).
lymph node metastasis (1 paper, 2023). "Most notably, we observed a significant association between the absence of CDH16 and lymph node metastasis (LNM), as well as distant metastasis." (PMID 37899424, 2023).
mesothelioma (1 paper, 2023). A usually malignant and aggressive neoplasm of the mesothelium which is often associated with exposure to asbestos. "An additional large section analysis revealed a CDH16 positivity in all 12 nephrogenic adenomas of the urinary bladder (9 strong, 3 moderate) and absence of CDH16 staining in 3 peritoneal and 2 mesotheliomas of the tunica albuginea." (PMID 37558687, 2023).
metastasis (1 paper, 2023). The spread or migration of cancer cells from one part of the body (where they first appeared) to another. "The loss of CDH16 expression was associated with aggressive PTC characteristics including bilaterality, multifocality, extrathyroidal extension, tall cell variant, lymph node metastasis (LNM) and distant metastasis." (PMID 37899424, 2023).
Sepsis (1 paper, 2020). Sepsis is defined as life-threatening organ dysfunction caused by a dysregulated host response to infection. "ROC curve analysis revealed that proteins (PARK7 and CDH16) could accurately discern sepsis-induced AKI patients, with the AUCs being 0.900 and 0.898, respectively." (PMID 32194432, 2020). "Therefore, PARK7 and CDH16 were confirmed to be novel biomarkers after validation in sepsis human patients." (PMID 32194432, 2020). "PARK7 and CDH16 could accurately discern sepsis-induced AKI patients with high AUC." (PMID 32194432, 2020). "AXL, CDH16, PARK7, and PGLYRP2 were significantly changed in the urine of patients suffering from sepsis-induced AKI." (PMID 32194432, 2020).
type 2 diabetes (1 paper, 2020). "Although the roles of Serpina11, Cdh16, Lrrc27, and Lrrc66 in regulating islet function remain unclear, Acod1 is known to be important in modulating the immune system and mitochondrial function, and Fgf21 can protect against type 2 diabetes in mice by increasing insulin expression and secretion." (PMID 32527043, 2020).
tumor (12 papers, 2005 to 2024). "Although the loss of CDH16 expression was unrelated to age, gender, tumor size and disease stage, it exhibited strong associations with several other aggressive features like tall cell variant, extrathyroidal extension, multifocality and bilateral tumors." (PMID 37899424, 2023). "Overall, 40 (26.3%) of 152 tumor categories showed detectable CDH16 expression and 19 (12.5%) tumor categories included at least one case with strong positivity." (PMID 37558687, 2023). "A CDH16 positivity was also seen in up to 8% of cases in 19 additional tumor categories but the staining was only weak to moderate in the vast majority of these cases." (PMID 37558687, 2023). "Our successful analysis of 13,424 tumors from 150 entities identified CDH16 expression in 40 of 152 analyzed tumor categories and enabled a ranking of tumor types according to their CDH16 positivity rate." (PMID 37558687, 2023). "Data from publicly available RNA databases suggest that CDH16 expression can—less commonly—also be found in other tumor entities including cervical, endometrial, and ovarian cancers." (PMID 37558687, 2023). "By contrast, CDH16, marker of the epithelial phenotype, was significantly less expressed in tumor cells than in normal thyrocytes." (PMID 24069422, 2013). "Nineteen further tumor entities showed a weak to moderate CDH16 staining in up to 8% of cases." (PMID 37558687, 2023). "Furthermore, by analyzing a small cohort of 35 PTC patients, they demonstrated a significant correlation between low expression of CDH16 and tumor size, stage and LNM." (PMID 37899424, 2023). "Cadherins CDH19, CDH16, CDH11 were found to be down regulated in OTSCC tumor as a read out of EMT process." (PMID 27280700, 2016). "Various further tumor entities showed positive staining either for PAX8 or CDH16 but not for both." (PMID 39105782, 2024). "However, immunohistochemical analyses of CDH16 expression are so far lacking for most tumor entities." (PMID 37558687, 2023). "For the distinction between a renal cell origin and a non-renal origin of tumors (including all other tumor entities of our study), sensitivity was 88.1% and specificity 87.2% for PAX8, while sensitivity was 85.3% and specificity 95.7% for CDH16." (PMID 39105782, 2024).
cancer (4 papers, 2015 to 2025). A tumor composed of atypical neoplastic, often pleomorphic cells that invade other tissues. "Previous studies have shown an interaction between CDH16 and other cancer genes." (PMID 37899424, 2023). "The synergistic effect of TERT and CDH16 on cellular adhesion and cancer progression may explain the worse DFS when TERT mutation and CDH16 loss coexist." (PMID 37899424, 2023).
infection (2 papers, 2019 to 2020). The state of being infected such as from the introduction of a foreign agent such as serum, vaccine, antigenic substance or organism. "The diagnostic sensitivity and specificity of PARK7 and CDH16 were higher than those of neutrophil gelatinase-associated lipocalin (NGAL), which was used to diagnose AKI, particularly infection-mediated AKI." (PMID 32194432, 2020). "Nevertheless, the infection was also able to repress extracellular exosome-related genes, such as complement C7 (C7) in the R line of the HSF flock, and fibroblast growth factor 9 (FGF9), cadherin 16 (CDH16), and FGG, in the R line of the TSF flock." (PMID 30678719, 2019).
CDH16 also shares sentences with these, for which no sentence is quoted: urothelial carcinoma (2 papers); Achalasia (1); adenoma (1); breast carcinoma (1); carcinoma of the ovary (1); carcinomas of the uterus (1); carcinosarcoma (1); chromophobe carcinomas (1); clear cell carcinomas (1); Constipation (1); Hypertension (1); intraepithelial neoplasia (1); kidney tumors (1); lung carcinoma (1); metastatic tumor (1); neuroendocrine neoplasm (1); oncocytic tumour (1); ovary (1); papillary carcinoma (1); papillary renal cell carcinoma (1); Polydipsia (1); Polyuria (1); renal diseases (1); renal medullary carcinoma (1); thyroid (1).